TNF (tumor necrosis factor)
Diseases named in the same sentence as TNF in open-access papers (continued):
Sharing a sentence is not in itself a finding about the gene and the disease.
Insulin resistance (continued). "Indeed, targeting IL-1β, IL-1β receptor, TNF-α, TLRs, T and B lymphocytes were effective in reducing blood glucose levels, insulin resistance and other metabolic markers in obesity." (PMID 28974032, 2017). "Thus, while the actions of HMGB1 on insulin resistance remain understudied, work from multiple systems suggests that HMGB1 can regulate TNFα and that HMGB1 can be linked to members of the insulin resistance pathway." (PMID 28542588, 2017). "Furthermore, M1 macrophages secrete pro-inflammatory cytokines including TNFα, IL-1β, and IL-6, some of which can directly alter insulin receptor signaling in adipocytes, leading to insulin resistance." (PMID 29163218, 2017). "TNF-α, PPARγ, and ERK are implicated in insulin resistance in metabolic syndrome." (PMID 29340106, 2017). "In addition, it decreased the expression of interleukin-1β and tumor necrosis factor-α, which are the key proinflammatory cytokines involved in insulin resistance; besides, it reduced the expression of NLRP3 inflammasome." (PMID 28928791, 2017). "However, if prolonged, the elevated TNF-α level can be deleterious, even leading to insulin resistance by downregulating the tyrosine kinase activity of the insulin receptor." (PMID 29163201, 2017). "Alternative M2 macrophages sustain insulin sensitivity via the secretion of anti-inflammatory cytokines such as IL-4 and IL-13, while classical M1 macrophages secrete pro-inflammatory cytokines such as TNF-α, IL-6, and IL-1β, which, in turn, leads to insulin resistance and NASH." (PMID 28420094, 2017). "As there is a significant association between β-cell damage and inflammation, this study sought to assess the host circulating levels of pro-inflammatory cytokines TNF-α and IL-6 as they are known to play an important role in the pathogenesis/progression of insulin resistance." (PMID 28077129, 2017). "The authors suggested that the activation of tumor necrosis factor-alpha by short chain C18Cer and C18:1Cer may contribute to insulin resistance in patients." (PMID 28714882, 2017). "This implies that TNF-α may be critical in mediating insulin resistance in mice chronically fed fructose." (PMID 28555043, 2017). "Finally, we investigated the effect of neutralising ADAM19 on diet induced weight gain, insulin resistance in vivo, and liver TNF-α levels." (PMID 28265178, 2017). "Potential carcinogenic mechanisms include inflammation with increased release of tumor necrosis factors (TNF)-alpha and interleukin 6, altered release of adipokines through insulin resistance and inflammation, lipotoxicity inducing oxidative stress and DNA damage." (PMID 28937622, 2017). "We hypothesized that TNF-α could increase the transcytosis of PA across CMECs and therefore facilitate PA-induced cardiac insulin resistance." (PMID 28304381, 2017). "Some pro-inflammatory cytokines synthesized by lymphocytes and keratinocytes in psoriatic skin, including IL-6, IL-17 and TNF-alpha, may contribute to systemic insulin resistance, a common feature of NAFLD." (PMID 28905102, 2017). "Increases in the levels of pro-inflammatory cytokines, such as interleukin-6 (IL-6) and tumor necrosis factor α (TNF-α), are observed in individuals with insulin-resistance, which may induce bone loss by stimulating osteoclast activity." (PMID 28704413, 2017). "In particular, hepatic macrophages, which include both resident Kupffer cells and recruited bone marrow-derived macrophages, are the major immune cells that secrete inflammatory mediators, such as tumor necrosis factor (TNF)-α and interleukin (IL)-1β, leading to systemic insulin resistance and NASH." (PMID 28420094, 2017). "TNF-α promotes atherosclerosis by endothelial dysfunction, promotes oxidative stress and is present in early atherosclerosis, in addition to being involved in dyslipidemia and insulin resistance." (PMID 28185008, 2017). "Therefore, elevated IL-6 and TNF-α serum levels can lead to insulin resistance and the occurrence of sarcopenia." (PMID 28701179, 2017).
Insulin resistance (continued). "Insulin resistance is a result of elevated levels of TNF-α, which also enhances PAI-1 expression; therefore, MnP-mediated reduction in TNF-α and PAI-1 levels synergize to inhibit steatosis and would likely be effective in reducing the risk for thrombosis and atherosclerosis." (PMID 29104232, 2017). "It follows then that blockade of TNF-α may lead to decreased insulin resistance, decreased β-cell apoptosis, and improvement in blood sugar control and general inflammation in patients with metabolic syndrome and diabetes." (PMID 29721512, 2017). "Therefore, it was suggested that periodontal treatment is effective in improving metabolic control in patients with T2DM, possibly through reduction in the serum concentration of TNF-α and decreased insulin resistance." (PMID 28431542, 2017). "Moreover, evidence turned out those levels of TNF-α in liver and serum from patients with MS who has the typical syndrome found a similar association between TNF-α and insulin resistance." (PMID 28241808, 2017). "The anti‐insulin resistance effect of ABE in TNF‐α‐induced adipocyte could be due to the inhibition of macrophage and adipocyte inflammation." (PMID 28572933, 2017). "Adipocytokines such as leptin, adiponectin, resistin, interleukin-6 (IL-6) and tumor necrosis factor-α (TNF-α) are mediators produced by adipocytes which have important roles in the pathophysiology of insulin resistance, inflammation, hypertension, endothelial dysfunction and atherosclerosis." (PMID 28747175, 2017). "Adipokines and free fatty acids released from adipose tissue stimulate the activity of macrophages, which express the proinflammatory cytokines TNF-α and IL-6; these factors interfere with the physiological function of adipocytes and induce the development of insulin resistance in adipocytes." (PMID 28900399, 2017). "In addition, vascular insulin resistance and dysfunction were reversed by the treatment with anti-TNF-α antibodies." (PMID 27766104, 2016). "TNF-α played a role in the pathogenesis of insulin resistance." (PMID 27764100, 2016). "For instance, skeletal muscle insulin resistance can be achieved by treatment of muscle cells with high nutrients (amino acids, glucose, and lipids) or pro-inflammatory factors such as tumor necrosis factor alpha (TNFα)." (PMID 28248217, 2016). "Interestingly enough, these cytokines have been implicated in insulin resistance (TNF-α, IL-6, and IL-1β), atherosclerotic plaque destabilization (IL-18), and future cardiovascular events (IL-6, IL-18, IL-1β, and TNF-α)." (PMID 27034691, 2016). "Briefly, pro-inflammatory cytokines, including Interleukin (IL)-1β, IL-6, and tumor necrosis factor (TNF)α, are elevated in T2D subjects, where they have been shown to promote insulin resistance in the adipose tissue, liver, and muscle, and β-cell failure in the pancreas." (PMID 26861388, 2016). "EPA and DHA can both decrease TNF-α levels and improve insulin resistance." (PMID 27544079, 2016). "The proinflammatory cytokine tumor necrosis factor-α (TNF-α) is synthesized and released by adipocytes and may play a role in the induction of insulin resistance." (PMID 26942201, 2016). "The mechanism of TNF-α to participate in insulin resistance and androgen excess could be of potential research interest in PCOS." (PMID 27764100, 2016). "Studies have highlighted the fact that insulin resistance is a characteristic feature of NAFLD and is caused by a variety of factors, including soluble mediators derived from immune cells and/or adipose tissue, such as TNF-α and IL-6." (PMID 27247565, 2016). "TNF is also synthesized in the adipose tissue and may act on glucose metabolism through the increase in lipolysis, and consequently contribute to insulin resistance." (PMID 26742100, 2016). "In addition, IL-6 and TNF-α promote insulin resistance in skeletal muscle and liver as well as proinflammatory activity in synovial tissue." (PMID 27964760, 2016).
Insulin resistance (continued). "CCL2 recruits macrophages to the adipose tissue, resulting in even more local cytokine production and perpetuating the inflammatory cycle; TNF-α and IL-6 induce a state of insulin resistance in adipocytes, which stimulates triglyceride lipolysis and fatty acid release into the circulation." (PMID 27247565, 2016). "It is well established that TNF-α induces insulin resistance." (PMID 27562094, 2016). "Thus, ILG alleviates TNF-α-mediated insulin resistance in adipocytes, presumably through inhibition of NF-κB activation." (PMID 26975571, 2016). "However, once insulin resistance arises, the inflammatory pathways are activated, and the levels of IL-6, IL-8, TNF-α, and CRP increase significantly and produce different degrees of injury in the body." (PMID 27187341, 2016). "As a result, ILG attenuated TNF-α-stimulated insulin resistance in adipocytes." (PMID 26975571, 2016). "Indeed, it has been shown that there is a relationship between TNF-α, oxidative stress and insulin resistance." (PMID 27023799, 2016). "Thus, quercetin suppresses the accumulation and activation of immune cells and the subsequent inflammation and systemic insulin resistance, probably by suppressing the expression of leptin, TNFα, and possibly IFNγ." (PMID 26499876, 2016). "Fat tissue produces adipokines, including leptin, adiponectin, TNF-α, IL-6, resistin and visfatin, which could be involved in activation of insulin resistance in pregnancy." (PMID 27423183, 2016). "Another mechanism that TNF-α induced insulin resistance in brown adipocytes could be via stress kinases." (PMID 26903879, 2016). "Moreover, MIF is a necessary mediator of TNF-α, which inhibits the insulin signal transduction leading to insulin resistance." (PMID 27298517, 2016). "Insulin resistance and the local biosynthesis of tumor necrosis factor alpha (TNFα) promote lipolysis in the adipose tissue, which stimulates the release of an additional pool of FFAs that may become preferential substrates for mitochondrial oxidation." (PMID 27417103, 2016). "Additionally, it has been shown that PPAR-γ agonists improve insulin resistance through inhibiting the effect of TNF-α in adipocytes." (PMID 26977143, 2016). "High levels of TNF-α have been shown to inhibit lipoprotein lipase activity in vitro and enhance the production of liver-derived TRL and adiposity has been reported to potentiate the effects of the TNFA polymorphism on lipid metabolism and insulin resistance." (PMID 27456841, 2016). "TNF-α level in insulin resistance is the most important indicator." (PMID 27042260, 2016). "In the liver, hepatic macrophages, which consist of resident Kupffer cells and recruited bone marrow-derived macrophages, are the major cells that produce inflammatory mediators, such as TNF-α and IL-1β, which are directly related to insulin resistance and the progression from NAFL to NASH." (PMID 27834813, 2016). "The uncontrolled hypertrophy of adipose tissue is characterized by the infiltration of macrophages, prominent source of proinflammatory cytokines, such as TNF-α and IL-6, that can block insulin signaling in adipocytes, providing a potential link between inflammation and insulin resistance." (PMID 26904104, 2016). "In addition, single infusion of the anti-TNF-α monoclonal antibody decreased insulin resistance in RA patients." (PMID 27340510, 2016). "Additionally, TNF-α and IL-6 are strong mediators of insulin resistance, which is the best-examined link in the pathogenesis of polycystic ovarian syndrome." (PMID 26942201, 2016). "The mechanisms underlying these effects of PM2.5 and their contributions to the development of systemic insulin resistance remain unclear, but excessive TNF-α production in the adipose tissue could induce lipolysis and thereby decrease adipocyte size." (PMID 27128347, 2016). "Additionally, clinical data have shown that other cytokines, such as TNF-α, leptin, and adiponectin, are also involved in insulin resistance." (PMID 27110299, 2016).
Insulin resistance (continued). "In a related study, it has been shown that high-fructose diet lowered IL-10, but did not change TNFα levels; however, PPARβ/δ deficiency made the insulin resistance apparent, in association with increased inflammatory markers, in adipose tissue of mice." (PMID 27066503, 2016). "Besides, these two pathological situations are marked with high concentrations of inflammatory mediators like tumor necrosis factor-α (TNF-α) and interleukin-6 (IL-6), known to play a pivotal role in insulin resistance." (PMID 27313878, 2016). "Therefore, the aim of the present study was to verify the influence of insulin resistance and TNF-α on the inflammatory process, oxidative stress, and disease activity in patients with RA." (PMID 27340510, 2016). "Several cross-sectional studies showed that insulin resistance and type 2 diabetes are associated with higher levels of C-reactive protein (CRP), interleukin-6 (IL-6), interleukin-1β, and tumor necrosis factor-α (TNF-α), which are markers of subclinical systemic inflammation." (PMID 27034691, 2016). "Elevated plasma TNF-α levels may be an important mediator of insulin resistance by impairing insulin signaling." (PMID 26666849, 2015). "The cytokines TNF-α and IL-1β can phosphorylate insulin receptor substrate-1 to induce insulin resistance, while the Islet amyloid polypeptide deposited in the pancreas can activate the NLRP3 (Nod-like receptor family, Pyrin domain containing 3) inflammasome to drive IL-1β secretion." (PMID 25802557, 2015). "TNF-α plays a role in the pathogenesis of insulin resistance." (PMID 26124830, 2015). "Similarly, inflammatory markers, such as TNF-α, IL-6, and FFA, which are the root causes of insulin resistance in diabetic patients, were greatly increased in control group, compared with the normal group." (PMID 25889508, 2015). "In addition to leptin an ever expanding number of adipokines are produced by the adipose tissue eg TNF-α, and IL-6 are known to promote insulin resistance which was corroborated here." (PMID 26061745, 2015). "Mice lacking TNFα because of a targeted null mutation were protected from insulin resistance caused by DIO or the ob/ob mutation." (PMID 26347815, 2015). "TNF-α, which is mainly produced by macrophages and, to a lesser degree, by adipocytes in obese adipose tissue, can disrupt insulin/insulin-like growth factor signaling and contribute to insulin resistance." (PMID 26413130, 2015). "Likewise, similar icv injections of anti-TLR-4 and anti-TNFα antibodies also decrease insulin resistance." (PMID 26415887, 2015). "Insulin resistance in this model also chronically elevates corticosterone, which, like chronic stress, contributes to microglial priming, increasing brain IL-1 and TNF responses." (PMID 25802557, 2015). "We then further investigated the prodiabetic mechanism of PP4 in TNF-α-induced insulin resistance." (PMID 26666849, 2015). "Report showed that PP4C could interact with IRS-4 and down-regulate IRS-411, we wondered whether PP4 was involved in TNF-α-induced insulin resistance by interacting with IRS-1." (PMID 26666849, 2015). "We next further investigated the role of PP4 activity in TNF-α-induced hepatic insulin resistance." (PMID 26666849, 2015). "These conversions may be caused by higher induction of TNF-α followed by the higher induction of p-JNK in GADD34 -deficient mice, which has been shown to be main pathway to insulin resistance." (PMID 26316333, 2015). "Insulin receptor substrate (IRS)-1 is one of the major targets in TNF-α-induced insulin resistance." (PMID 25623542, 2015). "Besides being inversely associated with serum TNF-α and IL-12, decreased IL-10 levels were significantly related to increased AHI, hyperinsulinemia, and insulin resistance." (PMID 25944984, 2015). "We also demonstrate that TNF-α at 2 h induced vascular insulin resistance as palmitate did at 18 h." (PMID 26055507, 2015).
Insulin resistance (continued). "To validate whether PP4 silencing could ameliorate TNF-α-induced hepatic insulin resistance in vivo, we injected AD-PP4 shRNA into the tail veils of C57BL/6J mice treated with or without TNF-α." (PMID 26666849, 2015). "Therefore, inhibition of TNFα actions in response to hyperglycemia would likely eliminate insulin resistance through multiple pathways." (PMID 25874611, 2015). "Agents that cause insulin resistance, such as TNF-α, have been shown to negatively regulate the expression and secretion of resistin, although paradoxically, studies have shown a contradictory increase in levels of resistin in response to TNF-α." (PMID 26097512, 2015). "Furthermore, pentoxifylline, a phosphodiesterase inhibitor, prevented TNFα production with only modest amelioration of insulin resistance in small studies of NASH patients." (PMID 26090470, 2015). "OA attenuated insulin resistance and decreased the levels of TNF-α and IL-6." (PMID 26843885, 2015). "Interestingly, pro-inflammatory cytokines such as TNF-α and IL-6, key players of the TLR4 signaling pathways, have also been implicated in the pathogenesis of impaired glucose uptake and insulin resistance in humans and rodents." (PMID 26539824, 2015). "Our data strongly suggested that PP4 might play a distinct role in TNF-α-induced hepatic insulin resistance." (PMID 26666849, 2015). "We assessed whether rescue of TUSC5 expression was sufficient to overcome TNFα-induced insulin resistance." (PMID 26240143, 2015). "To determine whether BAPN directly affects adipocyte function, we performed in vitro experiments in the TNFα-induced insulin resistance model in differentiated 3T3-L1 adipocytes." (PMID 26035864, 2015). "We next determined whether TUSC5 was necessary for the reversal of TNFα-induced insulin resistance by the PPARγ agonist rosiglitazone." (PMID 26240143, 2015). "Taken together, these data suggested that knock-down of PP4 could restore TNF-α-induced hepatic insulin resistance." (PMID 26666849, 2015). "Elevated IL-6 levels may contribute to disease development, by increasing the expression of cytokines like TNF-α known to induce insulin resistance, or by inducing insulin resistance itself." (PMID 26244048, 2015). "Rescue of TUSC5 expression did not protect adipocytes from TNFα-induced insulin resistance, loss of GLUT4, or inhibition of insulin signaling." (PMID 26240143, 2015). "In addition, there are associations among insulin resistance, abdominal obesity, and serum immune markers such as IL6 and TNFα." (PMID 26170888, 2015). "Thus, our data suggest that TNF-α plays an important role in myocardial insulin resistance resulting from MI." (PMID 26659007, 2015). "One possibility may be via the association between insulin resistance and WBC; another one, via proinflammatory cytokines, like TNF-α and IL-6 released from adipose cells, that elevate the WBC count." (PMID 26180744, 2015). "There may be several explanations on the effects of NAFLD on eGFR levels such as disturbed tumor necrosis factor system, imbalance of renin-angiotensin-aldosterone system, insulin resistance, and chronic inflammation." (PMID 26087253, 2015). "Additionally, salicylate has been reported to reduce insulin resistance in human umbilical vein endothelial cells and in the liver of Wistar rats fed a high fatty acid diet via reduced IKKβ and TNFα." (PMID 25874611, 2015). "db/db mice and TNF-α-treated C57BL/6J mice were used as hepatic insulin resistance animal models." (PMID 26666849, 2015). "In fact, the benefits of tumor necrosis factor alpha blockade in RA patients go far beyond the local (synovial) inflammatory process, and extend to other biological actions such as improvement of endothelial dysfunction and of insulin resistance." (PMID 25889060, 2015). "Taken together, these data strongly suggested that PP4 might be a linker between TNF-α and hepatic insulin resistance." (PMID 26666849, 2015).